MTOR (mechanistic target of rapamycin kinase)
Diseases named in the same sentence as MTOR in open-access papers (continued):
Sharing a sentence is not in itself a finding about the gene and the disease.
diabetes (continued). "Consequently, mTOR dysfunction has been implicated in the development of insulin resistance and diabetes." (PMID 37830621, 2023). "The activation of Sestrin2 could inhibit AMPK/mTOR signaling, promote autophagy and reduce the susceptibility of renal cells to diabetes-related damage." (PMID 37920252, 2023). "Moreover, mTOR dysregulation is also heavily implicated in diabetes-related complications, including nephropathy, heart failure, neuropathy, and diabetic osteoporosis." (PMID 37298150, 2023). "The mechanistic target of rapamycin (mTOR), a sensor of nutrient availability and growth factors, has been implicated in multiple diseases like cancer, diabetes, and neurodegenerative diseases; they are characterized by inflammation, as well as aging, referred to as “inflammaging”." (PMID 37765311, 2023). "Liraglutide, a type of GLP-1 receptor agonist, was figured out could decrease diabetes-induced cell loss and pyknosis and improve cognitive function that acts by increasing mTOR expression via the AMPK and PI3K/Akt pathways." (PMID 35371595, 2022). "The PI3K/AKT/mTOR signaling pathway may play crucial roles in the pathogenesis of obesity and diabetes mellitus, as well as metabolic syndromes, which could also be risk factors for cardio-metabolic disorders." (PMID 36671395, 2022). "In addition, mTOR signaling dysregulation has been linked to multiple human diseases, including obesity, diabetes, cancer, and neurological diseases." (PMID 36110218, 2022). "The results demonstrate that mTOR hyperactivation regulates autophagy, playing a critical role in the mechanism underlying PND, and reveal that the modulation of mTOR signaling could be a promising therapeutic strategy for PND in patients with diabetes." (PMID 34784444, 2022). "There are several causes of diabetes, including mTOR mediated metabolic problems, glucotoxicity, inflammation, mitochondrial dysfunction, increased oxidative stress or ER stress, caused by various programmed cell death such as apoptosis, autophagy, or necroptosis." (PMID 35300109, 2022). "The deregulation of mTOR is associated with diabetes, obesity, aging and various types of cancer." (PMID 33801030, 2021). "This review summarizes major findings and the latest information regarding the role of the mTORC1 signaling pathway in the pathogenesis of diabetes complications and suggests the potential pharmacological approaches to treat diabetes complications linked to mTOR deregulation." (PMID 35178356, 2021). "PRAS40 in conjunction with mTOR is closely associated with diabetes, cardiovascular diseases, and neurological diseases, such as improving insulin sensitivity, decreasing cardiomyocyte apoptosis after myocardial infarction and neuroprotectivity after transient focal cerebral ischemia." (PMID 33062146, 2020). "However, the causal association of mTOR pathways with diabetes is difficult to establish using observational studies in humans, and randomized controlled trials (RCTs) would be expensive." (PMID 32978410, 2020). "However, deregulated mammalian target of rapamycin (mTOR) signaling is implicated in the progression of cancer and diabetes, and the aging process in mammalian." (PMID 32194640, 2020). "Accordingly, diabetes-associated oxidative stress may activate the Akt-mTOR-AMPK signaling pathway in macrophages, which can be disturbed by the antioxidant asaronic acid." (PMID 32640667, 2020). "Furthermore, genetically reducing mTOR levels by eliminating the Raptor allele dramatically prevents podocyte injury and ameliorates the progression of glomerular dysfunction during diabetes." (PMID 32106480, 2020). "Given the important role of mTOR signaling in autophagy, lysosome dysfunction and autophagic deficiency due to overactivation of mTOR signaling may be involved in the pathogenesis of podocyte injury and glomerular damage in patients with diabetes." (PMID 32106480, 2020).
diabetes (continued). "However, mTOR hyperactivation is linked to several diseases such as cancer, since the kinase promotes tumor growth and proliferation, as well as diabetes, in which it contributes to insulin resistance." (PMID 32679743, 2020). "Since mTOR signaling is a key regulator of adipose tissue biology and function including thermogenesis, and endocrine system, the disabled state of mTOR pathways might be implicated in obesity and type 2 diabetes mellitus, cancer, aging, and so on." (PMID 30621146, 2019). "Furthermore, hyperactivation of the mTOR pathway by excessive food consumption is thought to be a critical factor which underlies diabetes." (PMID 30250008, 2018). "Elevated mTOR signaling has been found in AD patients and is linked to diabetes and aging." (PMID 30072954, 2018). "Interestingly, deficiency in mTor signaling has been implicated with insulin resistance and diabetes." (PMID 30072954, 2018). "The tuberin/mTOR pathway was implicated in apoptosis of tubular epithelial cells in diabetes." (PMID 27338360, 2016). "Current studies have shown that the PI3K/Akt/mTOR signaling pathway is abnormally activated in the kidneys of diabetes mellitus patients; however, the specific mechanism underlying this activation remains unclear." (PMID 25689721, 2015). "GLUT1, AMPK, HIF-1, and PI3K/Akt/mTOR are associated with type 2 diabetes pathogenesis and might be rational targets for diabetes therapy 34–36." (PMID 25644309, 2015). "Moreover, aberrant control of the PI3K-Akt regulatory axis or overactivation of mTOR has been suggested to play a causal role in many aging-related disorders, including cancer, type 2 diabetes mellitus, heart disease and neurodegeneration." (PMID 25853883, 2015). "The mTOR signaling may be vital for proper insulin signaling in patients with diabetes since the loss of mTOR leads to hypoinsulinemia, glucose intolerance, insulin insensitivity to glucose secretion, and a decrease in β-cell size." (PMID 26083118, 2015). "While acute use of mTOR inhibitors indeed reduces insulin resistance, chronic use of mTOR inhibitors, given for instance as immunosuppressants after transplantation, can induce insulin resistance and cause diabetes." (PMID 25973388, 2015). "Thus, the disruption of mTOR signaling is implicated in a wide array of diseases such as cancer, diabetes, and obesity." (PMID 24795562, 2014). "Previous studies have suggested that metformin may improve oxygenation and suppress the accumulation of HIF-1α in diseases associated with tumors or diabetes through the activation of the AMPK/mTOR pathway and the repression of oxygen consumption." (PMID 25310259, 2014). "Interestingly, new studies have linked mTOR signaling to the cell longevity pathways of SIRT1 that can also provide robust cardiovascular protection against models of experimental diabetes." (PMID 22545721, 2012). "Prior studies have implicated mTOR in nutrient sensing and diabetes." (PMID 17178004, 2006). "Importantly, the PI3K/AKT/mTOR pathway targeted by trifolirhizin is associated with other important diseases, including neurodegenerative disorders, autoimmune diseases, obesity, and diabetes." (PMID 39860257, 2025). "In addition, preclinical studies showed that niclosamide could improve diabetes and DKD through inhibition of the mammalian target of rapamycin (mTOR) signaling pathway that is implicated in diabetes and DKD progression." (PMID 36793092, 2023). "Therefore, streptozotocin may block signal transduction via dysregulation of the PI3K/Akt/mTOR pathway, which is subsequently associated with pathophysiological processes of diabetes mellitus and its complications." (PMID 35528246, 2022). "Debates continue on the therapeutic targeting of the AKT/mTOR axis under conditions associated with aging, neurodegenerative disorders, cancer, and diabetes, and whether the activation or inhibition of mTOR should be taken as a therapeutic approach is currently under investigation." (PMID 34215725, 2021).
diabetes (continued). "Considering the high prevalence of both vitamin D deficiency and diabetes mellitus and to clarify their relationship, this study was designed to shed light on the potential effects of vitamin D on DN, and the possible underlying mechanisms and interplays between autophagy and mTOR pathways." (PMID 32455017, 2020). "Our data indicates that a high glucose (25 mM) concentration (mimicking diabetes) significantly abrogated the effect of metformin on cell proliferation, cell death and cell cycle arrest in addition to loss of efficacy in inhibition of the mTOR pathway, a key metabolic pathway in TNBC cells." (PMID 30626087, 2019). "Thus, chrysin may encumber diabetes-associated formation of actin bundling and focal adhesion and mesangial cell motility through disturbing autophagy and mTOR pathway." (PMID 30634545, 2019). "It has been well established that mTOR plays the central role in the regulation of fundamental processes such as protein synthesis and autophagy, whereas deregulated mTOR signalling is implicated in diseases such as cancer, diabetes, as well as in the process of ageing." (PMID 29534520, 2018). "We have demonstrated for the first time a reduction in insulin signaling pathway proteins PI3-K/Akt/mTOR pathway in the brain of STZ treated rats that may be implicated as a dominant factor in neurodegeneration leading to cognitive dysfunction seen in diabetics." (PMID 30041644, 2018). "Therefore, our data suggests that suppression of mTOR activation and a reduction in the apoptotic resistance may overcome the tumorigenic effects of overnutrition and its associated link to diabetes and obesity." (PMID 28878358, 2017). "Drugs that suppress mTOR, such as rapamycin or metformin, have been shown to suppress cancer, type 2 diabetes and other age-related diseases; however, their ability to prevent age-related or other forms of hearing loss such as those linked to diabetes remain largely untested." (PMID 26977590, 2016). "Importantly, mTOR exists as 1 of 2 complexes and hyper-activity of the mTOR complexes 1 and 2 (mTORC1/2) has been implicated in tumor progression, pathological hypertrophy, diabetes and obesity." (PMID 26791164, 2016). "Investigation the effect of mTOR on the mitochondrial function in muscle can support the strategies for understanding of the mechanism of exercise treatment on the diabetes and other chronic diseases." (PMID 40950953, 2025). "There is growing evidence that mTOR pathway activity accelerates aging and the development of age-related diseases including cancer, atherosclerosis, diabetes, and declining immune function." (PMID 40620657, 2025). "mTOR inhibitors must be used with caution in patients with poorly controlled diabetes, hyperlipidemia, or severe pulmonary disease due to risks of metabolic abnormalities and pneumonitis." (PMID 40361453, 2025). "HIIT, vitamin D3 injection, and their combined treatment significantly decreased the levels of Beclin-1, Fyco-1, and cathepsin D and increased the levels of mTOR and pmTOR compared to the diabetes control group (p < 0.001)." (PMID 40144137, 2025). "The role of autophagy in microvascular remodeling in diabetes is actively discussed, particularly regarding interactions with HIF1α, mTOR, and the Bnip3/FoxO3a axis." (PMID 41169477, 2025). "Another basic research, through in vivo and in vitro experiments, revealed that asprosin alleviates diabetes-induced myocardial fibrosis by suppressing excessive autophagy mediated by the AMPK/mTOR/ULK1 pathway." (PMID 41458540, 2025). "The mTOR pathway plays a pivotal role in the pathogenesis of diabetes by regulating the energy balance and metabolism." (PMID 39944225, 2025). "Inhibiting PI3K/Akt/mTOR signaling restored autophagy (Beclin1 and LC3-II expression) and improved pain thresholds, suggesting that mTOR overactivation contributes to metabolic dysfunction in diabetes." (PMID 40218884, 2025).
diabetes (continued). "Studies have shown that genes associated with the PI3K/AKT pathway (e.g., MMPs) are upregulated in placental tissues of GDM patients, and this pathway, together with Jak-STAT and mTOR signaling, participates in diabetes-related pathological processes in GDM." (PMID 41460830, 2025). "Dysregulation of mTOR activity in patients with obesity and diabetes affects insulin sensitivity and lipid metabolism." (PMID 40547482, 2025). "Accumulating evidence suggests that mTOR/S6K signaling is involved in diabetes, cancer, and obesity." (PMID 39911324, 2025). "The protein mTOR was significantly (p < 0.001) decreased in diabetic rats compared to the non-diabetes group rats, was significantly (p = 0.001) increased in diabetic rats treated with metformin compared to diabetic rats." (PMID 40362714, 2025). "The CMAP database identified both known diabetes drugs (e.g., sulfonylureas), as well as drugs that target pathways known to be involved in diabetes pathogenesis (e.g., mTOR inhibitors)." (PMID 40595617, 2025). "In patients with obesity and diabetes, altered acetylation or phosphorylation of mTOR disrupts its role in insulin signaling, impairing glucose metabolism and contributing to insulin resistance." (PMID 40547482, 2025). "Intensive analysis of perturbed pathways is highly important, especially in diabetes where genes and proteins with high correlations were found to be involved in pathways related to insulin signaling, e.g., fatty acid metabolism and mTOR signaling." (PMID 41007744, 2025). "Regarding anabolic signaling pathways, the phosphorylation levels of key proteins, including AKT, mTOR, and rpS6, were differentially affected by diabetes and RSV treatment." (PMID 40004135, 2025). "MSC-exos also ameliorated DN by autophagy induction through the mammalian target of rapamycin (mTOR) signaling pathway in a rat model of streptozotocin-induced diabetes mellitus." (PMID 38252384, 2024). "Dysregulation of mTOR signaling contributes to many human diseases, including cancer, diabetes, and obesity." (PMID 39770519, 2024). "In these networks, ATGL (Pnpla2), is a prominent protein of the lipid droplet cluster, and STRING analysis connects this protein to diabetes related pathways including mTOR signaling and amyloid formation." (PMID 39562539, 2024). "Many studies have demonstrated the effect of mTOR dysregulation on metabolic diseases such as diabetes, obesity, and other cardiovascular diseases." (PMID 38892329, 2024). "Deregulation of mTOR signalling, which plays a key role in regulating autophagy, has been reported in many human diseases, including diabetes, neurodegenerative diseases, and cancer." (PMID 38956661, 2024). "Rapamycin is a potent inhibitor of mTOR, a key regulator of cell growth, proliferation, and metabolism, and is known for its therapeutic potential in diseases such as cancer, diabetes, obesity, neurological disorders, and genetic conditions." (PMID 39408711, 2024). "The increased cardiac concentrations of p38 MAPK and mTOR in the diabetic group further affirm diabetes-induced myocardial changes in the diabetic group." (PMID 39239455, 2024). "Akt/mTOR signaling pathway dysregulation has been studied in neurological disorders such as AD, traumatic brain injury, brain tumors, epilepsy, autism, diabetes, and aging process." (PMID 38182004, 2024). "mTOR activation induces its phosphorylation enhancement, while hyperactivation of mTOR prompts IR and diabetes." (PMID 39456499, 2024). "p- mTOR levels significantly decreased in EX (f1, 20 = 110.2, P < 0.0001, EX effect) and increased T2D (f1, 20 = 531.0, P < 0.0001, diabetes effect) compared to CO group in muscle." (PMID 38212600, 2024). "In diabetes, mTOR is key in affecting insulin resistance and sensitivity, glucose uptake, and lipid metabolism." (PMID 39770519, 2024). "In diabetes, mTOR has been shown to play a key role in affecting insulin resistance and sensitivity, glucose uptake, lipid metabolism, and ketone production." (PMID 38892329, 2024).
diabetes (continued). "In cardiology, prolonged hyperactivation of mTOR signaling in diabetes worsens post-ischemic myocardial injuries by accelerating cardiomyocyte death, leading to cardiac remodeling and inflammatory responses." (PMID 39056712, 2024). "The results of this study point toward the role of mTOR as a predictor of the occurrence of diabetes-related microvascular complications in the future." (PMID 39261960, 2024). "The mTOR signaling pathway has frequently been found to be dysregulated in individuals with diabetes as well." (PMID 38539200, 2024). "Aberrant activation of mTOR signaling pathways can disrupt normal cellular metabolic homeostasis, leading to accelerated aging processes, metabolic disorders like diabetes and obesity, and notably, the development and progression of cancer." (PMID 38727317, 2024). "Sestrin2 was shown to play a principal role in regulating monocyte activation through the AMPK/mTOR pathway in diabetes and also AMPK mediates Sestrin2 in a feedback way." (PMID 37920252, 2023). "Dysregulation of the mTOR signaling pathway is related to neurodegeneration, aging, and the development of cancer and diabetes." (PMID 36690663, 2023). "Given the core position of the mTOR pathway in metabolic regulation and bone turnover, mTOR-targeted therapeutic strategies have the potential to combat diabetes-related bone diseases." (PMID 37298150, 2023). "Studies investigating the activation of mTOR signaling find that short-term treatment of mTOR activation protects podocytes in diabetes mellitus, but long-term activation can lead to proteinuria and progressive glomerulosclerosis." (PMID 36766754, 2023). "Nevertheless, many side effects have been reported since mTOR-i was introduced (delayed wound healing, proteinuria, severe pneumoniae, hyperlipidemia, diabetes, oedema and many others) which limited mTOR-i administration." (PMID 36675596, 2023). "Current clinical trials have mainly focused on alleviating diabetes and its complications with mTOR inhibitors, especially metformin." (PMID 37298150, 2023). "With the inhibition of PI3K/AKT/mTOR pathway, autophagy is enhanced and hyperalgesia is alleviated in diabetes rats." (PMID 37920252, 2023). "Since much research has been conducted on the mTOR signaling pathway, it was found that it plays a crucial role in the development and progression of diabetes, cancer, and ageing." (PMID 37324188, 2023). "Mammalian target of rapamycin (mTOR) is a Ser/Thr kinase, which participates in a number of physiological and pathological processes, such as growth, signal integration, cancer, diabetes, and aging." (PMID 37841556, 2023). "The inhibition of mammalian target of rapamycin (mTOR) with rapamycin (RAPA) provides protection against myocardial ischemia/reperfusion (I/R) injury in diabetes." (PMID 38132140, 2023). "1,25(OH)2D3 provides a potential benefit in the regulation of the mTOR signaling pathway by stimulating DNA-damage-inducible transcript (DDIT4) expression in the treatment of diabetes." (PMID 36820117, 2023). "Dysregulation of the mTOR kinase pathway is reported in the pathogenesis of numerous human diseases, including cancer, diabetes, cardiovascular and neurological diseases." (PMID 37097377, 2023). "In the present study, we found that the treatments not only increased p70S6K expression and decreased 4E-BP1 expression but also regulated pAkt and mTOR, which are typically downregulated in diabetes." (PMID 38020198, 2023). "The mTOR pathway is a master nutrient sensor, which plays a key role in obesity and other metabolic disorders such as diabetes." (PMID 37245847, 2023). "Diabetes reduces phosphatidic acid in the retina, leading to decreased mTOR signaling and increased neuronal cell and RPC death." (PMID 37978169, 2023). "It is likely that diabetes activates TSC-mTOR signaling by inactivating AMPK, which inhibits the ULK kinase complex and restricts the initiation of autophagy because mTOR negatively regulates autophagy." (PMID 36841820, 2023).